GLP1R (glucagon like peptide 1 receptor)
Diseases named in the same sentence as GLP1R in open-access papers (continued):
Sharing a sentence is not in itself a finding about the gene and the disease.
arteriosclerosis (4 papers, 2018 to 2021). A vascular disorder characterized by thickening and hardening of the walls of the arteries. "Incretin signaling is known to prevent the development of arteriosclerosis by the relaxation response in endothelial cells via the GLP-1R." (PMID 34360682, 2021). "In vascular smooth muscle cells, GLP-1R stimulation prevents the development of arteriosclerosis." (PMID 34360682, 2021). "Therefore, it is likely that incretin-based therapy shows favorable effects on the development of arteriosclerosis through the reduction of blood glucose levels and their direct effects on arterial cells via GLP-1R." (PMID 34360682, 2021). "Second, incretin signaling plays a crucial role against arteriosclerosis, but incretin sensitivity in arteries is also weakened, at least partially, due to downregulation of GLP-1R expression, which we think may facilitate the development of arteriosclerosis." (PMID 34360682, 2021). "However, GLP-1R expression in arterial cells is also reduced under diabetic conditions and thus GLP-1RA shows more protective effects on arteriosclerosis at an early stage of T2DM." (PMID 34360682, 2021). "In addition, although GLP-1R is expressed in various cell types, it was not clearly elucidated how GLP-1RA can retard the progression of arteriosclerosis." (PMID 34360682, 2021).
cocaine use disorder (4 papers, 2021 to 2025). A substance-related disorder that involves the recurring use of cocaine despite negative consequences. "Altogether, our study reveals the novel effect of Ex4 on the reinstatement of cocaine-induced CPP and suggests that GLP-1R agonists appear to be highly promising drugs in the treatment of cocaine use disorder." (PMID 35069139, 2021).
coronary atherosclerosis (4 papers, 2021 to 2024). Atherosclerosis of the coronary vasculature. "Human studies showed a protective role of GLP-1R in the progression of coronary atherosclerosis through several pathways associated not only with metabolism but also with the polarization of macrophages." (PMID 39741663, 2024). "GLP-1R may regulate the polarization of macrophages toward M2, thus playing a protective role in the progression of coronary atherosclerosis." (PMID 33854404, 2021). "Glucagon-like peptide-1 receptor agonists (GLP-1 RAs) have pleiotropic effects, including preventing the development and progression of coronary atherosclerosis, epicardial coronary artery vasospasms, and structural/functional changes in coronary microvasculature." (PMID 38540106, 2024).
gastrinoma (4 papers, 2020 to 2023). "Because it is expressed in gastrinoma and bronchial lung cancer, it holds great promise for molecular imaging of NENs when the GLP-1R is negative." (PMID 37780209, 2023).
hypothyroidism (4 papers, 2022 to 2025). Abnormally low levels of thyroid hormone. "Oral semaglutide is a glucagon-like peptide-1 receptor agonist approved for T2DM management; however, its impact on MetS parameters in patients with coexisting hypothyroidism remains insufficiently explored." (PMID 41635458, 2025). "In comparison with PTU-treated rats, YJT treatment inhibited GLP-1R expression together with a drop in the serum GLP-1 levels, relieving hypophagia in hypothyroidism." (PMID 37270649, 2023).
lymphedema (4 papers, 2024 to 2025). Excess fluid collection in tissues, causing swelling. "Recent clinical evidence supports the therapeutic potential of glucagon-like peptide-1 receptor agonists (GLP-1RAs) in managing breast cancer-related lymphedema." (PMID 41403736, 2025). "Glucagon-like peptide-1 receptor agonists (GLP-1RAs), such as liraglutide and semaglutide, offer a revolutionary therapeutic approach by addressing both metabolic and vascular components of lymphedema." (PMID 41403736, 2025).
malnutrition (4 papers, 2021 to 2025). Inadequate nutrition resulting from poor diet, malabsorption, or abnormal nutrient distribution. "The potential weight loss effects of GLP-1R agonsits, however, are of particular concern for stimulant users who may have preexisting malnutrition status." (PMID 40009667, 2025).
nephrolithiasis (4 papers, 2022 to 2025). The presence of a calculus in the pelvis of the kidney; this is most often composed of mineral salts and proteins. "Glucagon-like peptide-1 receptor agonists (GLP-1 RAs) are also popular, but they are also associated with serious AEs like gastrointestinal disorders, hypotension, syncope, arthritic disorders, nephrolithiasis, interstitial nephritis, and drug-induced pancreatitis." (PMID 41011264, 2025).
ocular hypertension (4 papers, 2020 to 2025). Abnormally high intraocular pressure. "The effect of GLP-1R agonist administration on ON axon survival in ocular hypertension was more variable." (PMID 37362000, 2023).
pulmonary arterial hypertension (4 papers, 2019 to 2025). Pulmonary arterial hypertension (PAH) is a group of diseases characterized by mean pulmonary artery pressure >20 mmHg and elevated pulmonary arterial resistance leading to right heart failure. "Meanwhile, Glucagon-like peptide 1 receptor agonists attenuate autophagy via Drp1/NOX- and Atg-5/Atg-7/Beclin-1/LC3β pathways to improve pulmonary hypertension." (PMID 37491292, 2023).
subarachnoid hemorrhage (4 papers, 2021 to 2025). A serious neurological disorder characterized by intracranial hemorrhage into the subarachnoid space. "GLP-1R stimulation improves acute brain injury after subarachnoid hemorrhage by reducing neuronal damage and inflammation." (PMID 40224490, 2025). "In this study, we investigated the role of Exendin-4 (Ex-4), a glucagon-like peptide 1 receptor (GLP-1R) agonist, in blood-brain barrier (BBB) disruption after subarachnoid hemorrhage (SAH) in rats." (PMID 35002615, 2021).
amyloid (3 papers, 2022 to 2025). "It reshapes the gut microbiota structure and activates the GLP-1/GLP-1R pathway, thereby reducing amyloid deposition, enhancing synaptic plasticity, and alleviating cognitive dysfunction." (PMID 40657642, 2025). "This suggests that GLP-1R agonists forestall neuroinflammation by preventing insulin resistance and the mutually exacerbated amyloid pathology." (PMID 36117625, 2022). "GLP-1R agonists were shown to directly suppress microglial inflammation, while indirectly forestalling microglia-evoked astroglial activation, to protect neurons from amyloid toxicity." (PMID 36117625, 2022).
angioedema (3 papers, 2021 to 2025). Swelling involving the deep dermis, subcutaneous, or submucosal tissues, representing localized edema. "The only glucagon-like peptide-1 receptor agonist that has been mentioned to induce angioedema in literature is exenatide." (PMID 34987924, 2021). "Angioedema represents a rare adverse event of glucagon-like peptide-1 receptor agonists." (PMID 34987924, 2021).
aspiration pneumonia (3 papers, 2023 to 2026). "This cohort study investigates whether use of glucagon-like peptide-1 receptor agonists (GLP-1 RAs) is associated with postoperative aspiration pneumonia among patients undergoing common surgical procedures." (PMID 40036031, 2025).
cardiomyopathy (3 papers, 2023 to 2025). A disease of the heart muscle or myocardium proper. "Moreover, GLP-1R agonists suppress inflammation induced by cytokines produced in epicardial adipose tissue, which directly contributes to reduced risk of myocardial dysfunction and following cardiomyopathy." (PMID 40869284, 2025). "This review provides a comprehensive overview of the recent advances in the understanding of the GLP-1R-dependent and -independent actions of GLP-1 and its analogs in the protection against cardiomyopathies." (PMID 37375783, 2023).
cocaine abuse (3 papers, 2021 to 2025). Disorders related or resulting from use of cocaine. "Consequently, these results also provide additional support for the clinical availability of Ex4 or other GLP-1R agonists in the treatment of cocaine abuse." (PMID 35024034, 2021).
glucose metabolism disorder (3 papers, 2013 to 2024). "Among the six classes of antidiabetic drugs analyzed, GLP‐1R agonists were the only class of drugs to improve arterial stiffness in patients with abnormal glucose metabolism diseases." (PMID 37165762, 2023). "Among the six classes of antidiabetic drugs analyzed, GLP‐1R agonists constitute the only class of drugs that improves arterial stiffness in patients with abnormal glucose metabolism diseases." (PMID 37165762, 2023).
gout (3 papers, 2022 to 2025). A condition characterized by painful swelling of the joints, which is caused by deposition of urate crystals. "In summary, our findings indicate that GLP-1R plays a critical role in the development of gout by promoting macrophage recruitment into sites of inflammation." (PMID 35154099, 2022). "In monosodium urate (MSU) crystal-induced peritonitis, an experimental model of gout, the recruitment of macrophages, especially M2 macrophages, was significantly suppressed in GLP-1R knockout mice compared to wild-type mice." (PMID 35154099, 2022). "Whether GLP-1R is involved in inflammatory disease such as gout remains unclear." (PMID 35154099, 2022). "Therefore, GLP-1R may serve as a potential therapeutic target for gout." (PMID 35154099, 2022). "To further explore the effects of GLP-1R on the migratory ability of macrophages in vivo, we used MSU-induced peritonitis in mice as an animal model of gout." (PMID 35154099, 2022). "Given the important role of GLP-1/GLP-1R axis in regulating macrophage polarization, we hypothesize that it may regulate MSU-induced inflammation in gout." (PMID 35154099, 2022).
liver cancer (3 papers, 2024 to 2026). An epithelial or non-epithelial malignant neoplasm that arises from the liver. "Differ from STC2 and BIRC5 which were mainly expressed in liver cancer cells, EPO and GLP1R did not exhibit specific expression in a certain cell type, which could potentially be attributed to the fact that EPO and GLP1R may not predominantly expressed in HCC cell lines." (PMID 40458412, 2025).
liver inflammation (3 papers, 2021 to 2025). "In this model, semaglutide exerted protective effects on liver inflammation, fibrosis, and ROS accumulation, as well as the activated GLP-1R signaling pathway, leading to the inhibition of ubiquitin–proteasome system (UPS)-mediated proteolysis and to the promotion of myocyte myogenesis." (PMID 39125786, 2024).
memory impairment (3 papers, 2021 to 2024). "Geniposide has also been shown to act as a glucagon-like peptide-1 receptor (GLP-1R) agonist to reduce amyloid plaques and inhibit oxidative stress to alleviate memory impairment as well as synaptic loss." (PMID 34454545, 2021).
mental disorder (3 papers, 2025 to 2026). A disease that has its basis in the disruption of mental process. "Consistent and replicated evidence indicate that Glucagon-like Peptide-1 Receptor Agonists (GLP-1RAs) exert treatment and preventative effects across disparate neurologic and mental disorders, potentially through mechanisms involving autophagy." (PMID 41684077, 2026).
multiple sclerosis (3 papers, 2022 to 2025). A progressive autoimmune disorder affecting the central nervous system resulting in demyelination. "This is in agreement with previous studies on adult mice that have shown that GLP-1Rs are present in mature oligodendrocytes in multiple sclerosis, but ours appears to be the first study showing GLP-1R expression in neonatal oligodendrocytes." (PMID 41227362, 2025). "Multiple sclerosis (MS) still maintains increasing prevalence and poor prognosis, while glucagon‐like peptide‐1 receptor (GLP‐1R) agonists show excellent neuroprotective capacities recently." (PMID 34985189, 2022).
Nausea (3 papers, 2013 to 2025). A sensation of unease in the stomach together with an urge to vomit. "It seems, however, that while stimulation of some GLP-1R expressing neuronal populations is responsible for reducing food intake in association with nausea or aversion stimulation of others can lead to food intake reduction via mechanisms independent of nausea." (PMID 24133407, 2013). "However, the feeding suppression induced by NTS GLP-1R activation does not seem to rely on nausea induction, since at low doses of NTS Ex4, that still potently reduce food intake and reward, our current data and others show that Ex4 does not induce the PICA response." (PMID 25793511, 2015).
triple-negative breast carcinoma (3 papers, 2024 to 2026). An invasive breast carcinoma which is negative for expression of estrogen receptor (ER), progesterone receptor (PR), and human epidermal growth factor receptor 2 (HER2). "Herein, we report detection GLP-1R across multiple human tumor types and focus on triple-negative breast cancer (TNBC) for deeper analysis." (PMID 41542041, 2026).
Ventricular arrhythmia (3 papers, 2018 to 2025). "We sought to determine the effects of GLP-1R agonist exendin-4 (Ex4) on ventricular action potential duration (APD) and susceptibility to ventricular arrhythmia in the rat heart in vivo and ex vivo." (PMID 30354404, 2018). "To this end, we co-activated GABABR/GLP-1R and found that compared to single GLP-1RA, the post-MI ventricular arrhythmias was improved possibly via potentiation of GIRK." (PMID 41244817, 2025).
α-synucleinopathy (3 papers, 2021 to 2025). "GLP-1R agonism can reverse neuronal toxicity linked to synucleinopathy by decreasing oxidative stress, enhancing mitochondrial and lysosomal function, reducing α-synuclein aggregation, and improving neuronal survival." (PMID 40142784, 2025). "Recently, experiments establishing a rat model of α-synucleinopathy suggested that an increase in autophagy may be the fundamental mechanism underlying the neuroprotective effect of GLP-1R agonists, which is supported by our study." (PMID 35873704, 2022). "Their study demonstrated the basis of the potential benefits of GLP-1R agonism in neurons and astrocytes, and it pinpoints who is most likely to gain from GLP-1R agonism and underscores the effectiveness of GLP-1R agonism as a strategy to modify diseases in synucleinopathies." (PMID 40142784, 2025).
adenoma (2 papers, 2018 to 2019). A neoplasm arising from the epithelium. "In this study we showed that proliferation in pancreatic islets reflects on amplified GLP1-R expression in heterozygous mice at the age of 20 months, when 90% of the animals develops adenomas." (PMID 29335487, 2018). "A previous methylation microarray-based scanning has revealed that hypermethylation of GLP1R is a biomarker for CRC and adenoma." (PMID 30952955, 2019).
age-related macular degeneration (2 papers, 2025 to 2026). Age-related loss of vision in the central portion of the retina (macula), secondary to retinal degeneration. "There are also conflicting studies when the association of GLP-1R agonists and the development of age-related macular degeneration (AMD) is investigated." (PMID 41464694, 2025).
alopecia (2 papers, 2024 to 2025). Hair loss usually from the scalp. "Alopecia has recently been reported as a potential emerging adverse effect associated with glucagon-like peptide-1 receptor agonists (GLP-1RAs), which are widely prescribed for weight loss." (PMID 40951222, 2025). "In recent years, a relatively unexplored safety signal has emerged: the development of alopecia in patients treated with glucagon-like peptide-1 receptor agonists (GLP-1RAs), approved for weight reduction." (PMID 40951222, 2025).
anemia (2 papers, 2024 to 2026). A reduction in the number of red blood cells, the amount of hemoglobin, and/or the volume of packed red blood cells. "In this cohort study with 13 799 participants, initiation of SGLT2 inhibitors was associated with a 19% decrease in incident anemia risk compared with initiation of glucagon-like peptide-1 receptor agonists." (PMID 38436955, 2024).
brain injury (2 papers, 2023 to 2024). Acute and chronic (see also brain INJURIES, CHRONIC) injuries to the brain, including the cerebral hemispheres, CEREBELLUM, and brain STEM. "Hippocampal over-expression of GLP-1 in rats enhanced learning and memory, and activation of GLP-1R signaling in mice attenuated the severity of experimental brain injury, whereas Glp1r−/− mice exhibited enhanced seizure severity and neuronal injury after kainate administration." (PMID 39216535, 2024).
cocaine addiction (2 papers, 2018 to 2021). "Recent literature indicated that GLP-1R agonist Ex4 appears highly promising in attenuating the rewarding and reinforcing effects of cocaine addiction." (PMID 35024034, 2021).
colorectal tumors (2 papers, 2021 to 2026). "The same study assessed GLP-1r expression from human colorectal tumors and found the mRNA transcripts to be downregulated in the colorectal tumors compared to adjacent non-neoplastic tissue." (PMID 33916501, 2021).
Crohn disease (2 papers, 2020 to 2025). A gastrointestinal disorder characterized by chronic inflammation involving all layers of the intestinal wall, noncaseating granulomas affecting the intestinal wall and regional lymph nodes, and transmural fibrosis. "Glucagon-like peptides (GLP-1 and GLP-2) are two proglucagon-derived intestinal hormones that mediate distinct physiological functions through two related receptors (GLP-1R and GLP-2R) which are important drug targets for metabolic disorders and Crohn’s disease, respectively." (PMID 33239759, 2020).
cyst (2 papers, 2024 to 2025). A sac-like closed membranous structure that may be empty or contain fluid or amorphous material. "Therefore, it is necessary to investigate the expression of GLP-1R in cyst epithelium and the potential impact of GLP-1 agonism on cAMP levels." (PMID 39339816, 2024).
dermatomyositis (2 papers, 2022 to 2023). Dermatomyositis (DM) is a type of idiopathic inflammatory myopathy characterized by evocative skin lesions and symmetrical proximal muscle weakness. "Muscle biopsies of dermatomyositis and polymyositis patients demonstrate the presence of GLP-1R; GLP‐1R agonists ameliorated muscle weakness, muscle weight loss, and muscle inflammation through inhibiting muscle fiber necroptosis." (PMID 38292961, 2023). "We also examined the muscle specimens of dermatomyositis (DM) patients (n = 3), which is another subset of idiopathic inflammatory myopathy, for the expression of GLP‐1R." (PMID 35775116, 2022).
epilepsy (2 papers, 2019 to 2025). A brain disorder characterized by episodes of abnormally increased neuronal discharge resulting in transient episodes of sensory or motor neurological dysfunction, or psychic dysfunction. "Therefore, we investigated in the present study the possible anti-epileptic effect of liraglutide (GLP-1R agonist) against PTZ kindled epilepsy and its possible underlying mechanisms by targeting autophagy, apoptosis, oxidative stress and the Wnt pathway." (PMID 31091715, 2019).
glomerulosclerosis (2 papers, 2019 to 2024). A hardening of the kidney glomerulus caused by scarring of the blood vessels. "Nevertheless, beyond glycemic and blood pressure control, other potential mechanisms for preserving renal function with a GLP-1R agonist treatment include anti-inflammatory actions, reduced fibrosis, and reduced glomerular sclerosis." (PMID 38540270, 2024). "Furthermore, studies have identified that the absence of GLP1R can lead to spontaneous kidney damage, including albuminuria and glomerulosclerosis, conditions that worsen in the context of type-1 diabetes." (PMID 38540270, 2024). "As glomerulosclerosis develops by 4 weeks in CKD models and tubulointerstitial fibrosis develops by 8 weeks, we estimate that functioning tubules increase their expression of GLP-1R over the first 2 weeks, followed by decreased expression by week 8 as a result of tubular fibrosis and apoptosis." (PMID 30823876, 2019).